TTC12 (tetratricopeptide repeat domain 12)
Description:
Cytoplasmic protein that plays a role in the proper assembly of dynein arm complexes in motile cilia in both respiratory cells and sperm flagella.
Synonyms: FLJ13859; FLJ20535; TPARM; CILD45
Tractability: Antibody: its Gene Ontology location is reachable by antibodies, with high confidence; the Human Protein Atlas places it where antibodies can reach. PROTAC: ubiquitination databases record sites on it.
Gene: Protein-coding gene on chromosome 11 (113,314,579 to 113,383,544, forward strand). Ensembl gene ENSG00000149292.
Subcellular location: Cytoplasm
Subcellular location (Human Protein Atlas): Cytosol; Nuclear membrane; Plasma membrane
Gene Ontology:
Biological process: axonemal dynein complex assembly; sperm axoneme assembly
Cellular component: centrosome; cytoplasm
Genetic constraint (gnomAD): Loss-of-function variants: 51 observed, 68.96 expected, observed/expected ratio (o/e) 0.74, 90% interval 0.59 to 0.93. The upper end of that interval is the gene's LOEUF score, 0.93, which puts it in group 3 of 6, group 1 being the genes least tolerant of losing a copy. Missense variants: 687 observed, 731.41 expected, observed/expected ratio (o/e) 0.94, 90% interval 0.88 to 1. Synonymous variants: 257 observed, 279.41 expected, observed/expected ratio (o/e) 0.92, 90% interval 0.83 to 1.02.
Gene-disease validity (ClinGen):
ClinGen rates the evidence that TTC12 causes each of these diseases.
ciliary dyskinesia, primary, 45 (autosomal recessive): Definitive.
Homologues: Orthologues: chimpanzee TTC12 (96% identical), macaque TTC12 (91% identical), rabbit TTC12 (80% identical), guinea pig TTC12 (78% identical), dog TTC12 (78% identical), rat Ttc12 (77% identical), mouse Ttc12 (75% identical), pig TTC12 (69% identical), Drosophila melanogaster unc-45 (12% identical), Caenorhabditis elegans unc-45 (12% identical), Drosophila melanogaster Stip1 (9% identical), Drosophila melanogaster Sgt (4% identical), and 1 more. Paralogues in human: SPAG1 (14% identical), TOMM70 (14% identical), RPAP3 (13% identical), UNC45B (13% identical), UNC45A (13% identical), DNAAF4 (12% identical), STIP1 (11% identical), SPATA16 (9% identical), TOMM34 (8% identical), ST13 (7% identical), TTC31 (7% identical), SGTA (6% identical), and 6 more.
Diseases named in the same sentence as TTC12 in open-access papers:
TTC12 is named in the same sentence as 14 diseases in open-access papers, as found by Europe PMC text mining. Sharing a sentence is not in itself a finding about the gene and the disease. The quoted sentences say what the papers report.
male infertility (3 papers, 2023 to 2025). The inability of the male to effect fertilization of an ovum after a specified period of unprotected intercourse. "ICSI treatment was applied to male infertility and asthenoteratozoospermia caused by TTC12 variants." (PMID 37325566, 2023). "Thus, our genetic and experimental study convincingly identified loss-of-function variants of TTC12 in asthenoteratozoospermia-affected individuals in a Chinese infertile cohort, which confirmed the contribution of TTC12 to male infertility." (PMID 37325566, 2023). "However, solid TTC12 defects that cause asthenoteratozoospermia and male infertility in the Chinese population have not been reported." (PMID 37325566, 2023). "As it was recently shown that TTC12 variants can also cause asthenoteratozoospermia without a PCD phenotype, this gene was added to our most recent male infertility gene panel version." (PMID 39180390, 2025).
primary ciliary dyskinesia (3 papers, 2021 to 2023). A rare, genetically heterogeneous, primarily respiratory disorder characterized by chronic upper and lower respiratory tract disease. "TTC12 loss-of-function mutations cause primary ciliary dyskinesia and unveil distinct dynein assembly mechanisms in motile cilia versus flagella." (PMID 36273201, 2022). "Discovery of new disease genes—Four genes, i.e., TTC12, GAS2L2, DNAH9 and DNAJB13, whose mutations are responsible for Primary Ciliary Dyskinesia (PCD) have been identified through molecular and cellular studies performed in the framework of the RaDiCo-DCP cohort." (PMID 34715889, 2021). "Human tetratricopeptide repeat domain 12 (TTC12) is a recently-discovered gene involved in the assembly of ciliary and flagellar axonemes, and its biallelic variants have been reported to cause primary ciliary dyskinesia (PCD) in individuals from four separate families." (PMID 37325566, 2023).
alcoholism (1 paper, 2019). "TTC12 is a brain biomarker in alcoholism, and numerous studies have been performed on polymorphisms in this gene." (PMID 31428131, 2019).
ciliopathies (1 paper, 2022). "To the best of our knowledge, we provide the first genetic evidence to support the correlation between TTC12 variants and ciliopathies in the Chinese population." (PMID 36273201, 2022).
depression (1 paper, 2025). "This genomic region that harbors multiple known depression-associated genes (e.g., NCAM1, TTC12, DRD2) remained significant for depression and ischemic stroke." (PMID 40949012, 2025).
Infertility (1 paper, 2023). "The previous study included two unrelated infertile male adults from Turkey and Europe with TTC12 mutations." (PMID 37325566, 2023). "We also demonstrated that TTC12 deficiency-mediated infertility can be overcome by intracytoplasmic sperm injection (ICSI) technology." (PMID 37325566, 2023). "We also demonstrated that TTC12 deficiency-mediated infertility could be overcome by ICSI technology." (PMID 37325566, 2023). "Our results confirmed that TTC12 variants are related to PCD, suggesting that patients with asthenoteratozoospermia should pay attention to cilia-related phenotypes when they undergo infertility treatment." (PMID 37325566, 2023). "As expected, further examination of the three asthenoteratozoospermia-affected individuals with TTC12 mutants revealed a mild PCD-related nasosinusitis phenotype, a respiratory cilia impairment that was usually ignored when these individuals requested infertility-related counseling." (PMID 37325566, 2023).
leukemia (1 paper, 2022). A malignant (clonal) hematologic disorder, involving hematopoietic stem cells and characterized by the presence of primitive or atypical myeloid or lymphoid cells in the bone marrow and the blood. "AP000880.1 is possibly related to TTC12 and NCAM1 gene, which in turn plays an important role in the initiation of leukemia." (PMID 35719911, 2022).
cancer (2 papers, 2024 to 2025). A tumor composed of atypical neoplastic, often pleomorphic cells that invade other tissues. "Several top-ranking genes, such as MEIS1, ZDHHC11, CWH43, TTC12, and CDH22, have been supported by recent studies as playing roles in various cancers and aging-related processes." (PMID 39499149, 2024).
TTC12 also shares sentences with these, for which no sentence is quoted: Hypertension (1 paper); ischemic stroke (1); nephronophthisis (1); nicotine dependence (1); substance dependence (1); tumour (1).